EYA3 (EYA transcriptional coactivator and phosphatase 3)
Diseases named in the same sentence as EYA3 in open-access papers:
EYA3 is named in the same sentence as 21 diseases in open-access papers, as found by Europe PMC text mining. Sharing a sentence is not in itself a finding about the gene and the disease. The quoted sentences say what the papers report.
Ewing sarcoma (7 papers, 2015 to 2022). A small round cell tumor that lacks morphologic, immunohistochemical, and electron microscopic evidence of neuroectodermal differentiation. "EWS RNA binding protein 1/Fli-1 proto-oncogene, ETS transcription factor regulates EYA3 in Ewing sarcoma via modulation of miR-708, resulting in increased cell survival and chemoresistance." (PMID 34395419, 2021). "Surprisingly, the top two hits, EWSR1 and EYA3 both play a role in the development of Ewing sarcoma." (PMID 31494268, 2019). "EYA3, a DNA repair protein and transcriptional cofactor, is highly expressed in Ewing’s sarcoma cells and required for their survival and chemoresistance." (PMID 31494268, 2019). "The authors also showed that miR-708-5p and EYA3 expressions were negatively correlated in Ewing’s sarcoma patients." (PMID 29050362, 2017). "Restored miR-708 directly targeted EYA3 and reduced its expression, thus sensitized Ewing's sarcoma cells to the DNA-damaging drugs etoposide and DOX." (PMID 28978183, 2017). "Decreased expression of another miR, miR-708, induced EYA3 expression and led to drug resistance in Ewing's sarcoma." (PMID 28978183, 2017). "EYA proteins are involved in DNA repair and qRT-PCR evaluation of hMSC and Ewing sarcoma cell lines revealed that only EYA3 is consistently up-regulated in Ewing sarcoma." (PMID 26204834, 2015). "In Ewing sarcoma, miR-708 downregulation contributes to tumor progression via the consequently increased expression of EYA Transcriptional Coactivator and Phosphatase 3 (EYA3), which is a transcriptional activator involved in cancer cell survival, invasion, and chemoresistance." (PMID 35011736, 2022). "Furthermore, Ewing’s sarcoma patients with low miR-708-5p paired with high EYA3 expression had worse RFS rates." (PMID 29050362, 2017). "The authors thus proposed EYA3 as a novel mediator of chemoresistance in Ewing sarcoma." (PMID 28439237, 2017). "The reduction of EYA3 protein has negative effects on the survival of Ewing sarcoma." (PMID 28439237, 2017).
breast carcinoma (5 papers, 2012 to 2021). "Remarkable relation among EYA1, EYA2 and EYA3 genes with the LumB subtype are in accordance with the previous finding that EYA genes play an important role in breast cancer growth and metastasis as well as directing cells to the repair pathway upon DNA damage." (PMID 34112093, 2021). "A previous study reported that EYA3 interacts with PP2A to regulate the stability of c-Myc mRNA in breast cancer." (PMID 34395419, 2021). "In line with a tumor promotional role of the Eya3–PP2A complex, we demonstrate in mouse models of breast cancer metastasis that Eya3 that is unable to interact with B55α has reduced metastasis, and that knockdown (KD) of the B55α subunit inhibits metastasis." (PMID 29535359, 2018). "We demonstrate that KD of B55α, as expected, diminishes the interaction of the B55α regulatory subunit of PP2A with Eya3 in 66cl4 mammary carcinoma cells, demonstrating the specificity of our PLA experiments." (PMID 29535359, 2018). "In previous studies we have shown that the tyrosine phosphatase activity of Eya3 and Eya2 promotes single cell motility in breast cancer cells." (PMID 22545090, 2012). "To determine whether Eya3 can indeed dephosphorylate c-Myc at pT58, and is thereby stabilizing c-Myc via Eya3′s association with PP2A, we first generated Eya3 addback lines using the triple negative mouse mammary carcinoma cell line, 66cl439." (PMID 29535359, 2018). "The level of EYA3 in breast cancers is elevated when compared with non-cancerous tissues, thereby promoting cell migration and invasion of breast cancer cells." (PMID 34395419, 2021). "Furthermore, Eya3 and PP2A-B55α promote metastasis in a xenograft model of breast cancer, opposing the canonical tumor suppressive function of PP2A-B56α." (PMID 29535359, 2018).
pancreatic ductal adenocarcinoma (3 papers, 2021 to 2023). An infiltrating adenocarcinoma that arises from the epithelial cells of the pancreas. "Hsa_circ_0007895 (circEYA3)—derived from exons 2–6 of EYA3–facilitates the proliferation and progression of pancreatic ductal adenocarcinoma." (PMID 38042777, 2023). "Circ-EYA3 is elevated in pancreatic ductal adenocarcinoma (PDAC) tissues and cells, and higher levels of circ-EYA3 are significantly associated with poorer prognosis in PDAC patients." (PMID 34881248, 2021).
triple-negative breast carcinoma (3 papers, 2018 to 2025). An invasive breast carcinoma which is negative for expression of estrogen receptor (ER), progesterone receptor (PR), and human epidermal growth factor receptor 2 (HER2). "We have previously shown that Eya3 recruits PP2A–B55α to dephosphorylate pT58 on Myc, increasing Myc stability and enhancing primary tumor growth of triple-negative breast cancer (TNBC)." (PMID 40414499, 2025). "We chose the 66cl4 triple negative breast cancer (TNBC) system, due to previous evidence that Eya3 plays a role in the metastasis of TNBC13." (PMID 29535359, 2018).
breast tumor (2 papers, 2023 to 2024). "It had been reported that EYA3 enhanced breast tumor growth via regulating cytotoxic T cells and was associated with increased numbers of infiltrated CD8 + T cells." (PMID 37156847, 2023). "Given that the Eya3 and PP2A-B55α interaction plays a major role in promoting breast tumor growth and metastasis, inhibiting this interaction may serve as a potential therapeutic approach for breast and other Eya and Myc-driven cancers." (PMID 38796066, 2024).
pancreatic cancer (2 papers, 2011 to 2023). "In turn, the most commonly deleted gene was MYOCD, a cancer related gene which also displayed LOH in most of our cases (80%); other frequently deleted cancer-associated genes included the EYA3, NR2C1, PTAFR, and the DCC cancer associated genes which have also been involved in pancreatic cancer." (PMID 21811587, 2011).
Alzheimer disease (1 paper, 2008). A progressive, neurodegenerative disease characterized by loss of function and death of nerve cells in several areas of the brain leading to loss of cognitive function such as memory and language. "Among the genes being down-regulated in the brains of Eya3 mutants, several are reported to be down-regulated also in Alzheimer's disease, e.g. ARPP19, BIRC4, MT3, SYT1 or TTR." (PMID 19102749, 2008).
Arrhythmia (1 paper, 2013). Any cardiac rhythm other than the normal sinus rhythm. "The most potent compound tested, in terms of inhibition of EYA3 catalytic activity, was ODAA, a metabolite of the anti-arrhythmia drug Amiodarone (AMIO)." (PMID 24367676, 2013).
depressions (1 paper, 2015). "A polymorphism inASMT, the last gene in the melatonin synthesis pathway, is associated with circadian phase delay and perhaps with inadequate melatonin synthesis (factors that combined might augment or inhibit EYA3), and with depression and bipolar disorder." (PMID 26180634, 2015). "A genetic trend towards phase delay in melatonin offset may explain how depressions due to inadequate pars tuberalis EYA3 and low hypothalamic T3 might occur at any time of year, but a genetic predisposition to delay does not explain why symptoms should peak near or just after the Spring equinox." (PMID 26180634, 2015).
head and neck cancer (1 paper, 2019). A primary or metastatic malignant neoplasm affecting the head and neck. "In addition, EYA3 expression was assessed in head and neck cancer biopsies." (PMID 31801939, 2019).
kidney cancer (1 paper, 2023). Primary or metastatic malignant neoplasm involving the kidney. "In the study, we confirmed that the expression of EYA3 was higher in normal tissues than in kidney cancer tissues." (PMID 37156847, 2023).
myeloma (1 paper, 2023). "Thus, our data hint toward a role for EYA3 in regulating the survival decision upon bortezomib-induced genotoxic stress in primary myeloma cells." (PMID 37081258, 2023).
osteosarcoma (1 paper, 2021). A usually aggressive malignant bone-forming mesenchymal neoplasm, predominantly affecting adolescents and young adults. "EYA3 promotes chemotherapy resistance of osteosarcoma by regulating miR-708." (PMID 34395419, 2021).
Parkinson disease (1 paper, 2008). A progressive degenerative disorder of the central nervous system characterized by loss of dopamine producing neurons in the substantia nigra and the presence of Lewy bodies in the substantia nigra and locus coeruleus. "This short comparison between the differentially expressed genes in the Eya3 mutant mice with corresponding features in neurodegenerative disorders in human patients points to an interesting putative role of EYA3 in Alzheimer's and Parkinson's disease." (PMID 19102749, 2008). "Moreover, the SCA10 gene, which is down-regulated in the brain of the Eya3 mutants, is also down-regulated in patients suffering from Parkinson's disease." (PMID 19102749, 2008). "Therefore, future investigations of Eya3 function should focus on effects on aging mice and consider also effects related to neurodegenerative disorders like Alzheimer's or Parkinson's disease." (PMID 19102749, 2008).
prostate carcinoma (1 paper, 2021). A carcinoma that arises from epithelial cells of the prostate gland. "The results indicated that miR-223 overexpression or EYA3 knockdown both can reverse the function of circGNG4 on the prostate cancer cell proliferation, migration and invasion." (PMID 34395419, 2021). "Inhibition of miR-223 led to the elevated expression of tumor-promoting factor EYA3 and c-Myc, thus enhancing the malignant behavior of prostate cancer." (PMID 34395419, 2021). "In conclusion, the circGNG4/miR-223/EYA3/c-Myc regulatory pathway promoted the malignant progression of prostate cancer." (PMID 34395419, 2021). "In the present study, EYA3 was confirmed to promote the stability of c-Myc in prostate cancer cells." (PMID 34395419, 2021). "circGNG4 enhanced the expression of EYA3/c-Myc by sponging miR-223 to promote the growth of prostate cancer tumors in vivo." (PMID 34395419, 2021). "The circGNG4/miR-223/EYA3/c-Myc signaling axis may therefore be crucial for the development of prostate cancer, and may act as a potential therapeutic target for prostate cancer." (PMID 34395419, 2021). "Furthermore, EYA3 was highly expressed in prostate cancer tissues, which was demonstrated by qPCR and immunohistochemistry (IHC) detection, and EYA3 was also highly expressed in prostate cancer cell lines." (PMID 34395419, 2021). "However, the interaction between EYA3 and c-Myc in prostate cancer remains to be elucidated." (PMID 34395419, 2021).
pulmonary arterial hypertension (1 paper, 2019). Pulmonary arterial hypertension (PAH) is a group of diseases characterized by mean pulmonary artery pressure >20 mmHg and elevated pulmonary arterial resistance leading to right heart failure. "Together these observations establish EYA3 as a disease-modifying target whose function in the pathophysiology of pulmonary arterial hypertension can be targeted by available inhibitors." (PMID 31515519, 2019). "Here we report that levels of Eyes Absent 3 (EYA3) are elevated in pulmonary arterial smooth muscle cells from patients with pulmonary arterial hypertension and that EYA3 tyrosine phosphatase activity promotes the survival of these cells under DNA-damaging conditions." (PMID 31515519, 2019). "Here we report that inhibition of the Eyes Absent (EYA3) tyrosine phosphatase can attenuate DNA-damage repair, promote apoptosis of pulmonary vascular cells, and substantially reverse established vascular remodeling in a rodent model of experimental pulmonary hypertension." (PMID 31515519, 2019).
Right ventricular hypertrophy (1 paper, 2021). In this case the right ventricle is more muscular than normal, causing a characteristic boot-shaped (coeur-en-sabot) appearance as seen on anterior- posterior chest x-rays. "These miRNAs were all found to target the expression of EYA3 mRNA, which is involved in the onset of right ventricular hypertrophy." (PMID 33710774, 2021). "Similarly, several miRNAs are important in the onset of right ventricular hypertrophy, and the inhibition of EYA3 was proved to reverse vascular remodelling in rats." (PMID 33710774, 2021). "CircRNA‐0068481 and several miRNAs are important in the pathogenesis of right ventricular hypertrophy (VH), while the inhibition of eye absent transcriptional coactivator and phosphatase 3 (EYA3) was proved to reverse vascular remodelling in rats." (PMID 33710774, 2021).
schizophrenia (1 paper, 2023). A major psychotic disorder characterized by abnormalities in the perception or expression of reality. "We transformed these proteins to their encoding gene IDs and identified the top 20 genes as the most probable schizophrenia-risk genes, including the EYA3, CNTN4, HSPA8, LRRK2, and AFP genes." (PMID 37966892, 2023). "Therefore, we speculated that EYA3 may be a potential risk gene for schizophrenia." (PMID 37966892, 2023).
cancer (9 papers, 2011 to 2025). A tumor composed of atypical neoplastic, often pleomorphic cells that invade other tissues. "Our study found that EYA3 was positively correlated with the infiltration of immune cells in ccRCC, suggesting the participation of EYA3 in the regulation of cancer immunity." (PMID 37156847, 2023). "As one of the EYA family of proteins, currently, there are few research reports on the EYA3 gene in cancer." (PMID 37156847, 2023). "To begin, we explored the dysregulated transcriptional levels of the EYAs (EYA1, EYA2, EYA3, EYA4) family in 34 types of human common cancer." (PMID 37156847, 2023). "Those events occurred on pre-mRNA of 56 genes including well-known cancer-related genes PTPRC, IKBKB and HRAS, and genes coding for transcription factors ILF2, ATF2 and EYA3." (PMID 34543356, 2021). "We showed B55i can disrupt the Eya3 and PP2A–B55α interaction in vitro, and B55i expressed on a plasmid can increase Myc pT58 and reduce Myc protein level in TNBC cells, illustrating its potential as a cancer therapy." (PMID 40414499, 2025). "The tyrosine-phosphatase activity of EYA3 was shown to be critical for cell motility and invasiveness rather than proliferation, indicating that EYA3 promotes metastatic behavior in cancer cells." (PMID 27203207, 2016). "Given that targeting Myc still remains a major unrealized goal for cancer therapy, the direct inhibition of the Eya3–PP2A interaction by B55i may be a significantly less toxic means to target Myc in TNBC and other tumor types that overexpress Eya3." (PMID 40414499, 2025). "While chemotherapeutic-induced DNA damage may stimulate CHOP in normal cells, mutated or fused CHOP proteins may not activate miR-708-5p expression, resulting in increased EYA3 expression, efficient DNA repair, and cancer cell survival." (PMID 29050362, 2017). "Furthermore, because EYA3’s tyrosine phosphatase activity promotes DNA damage repair, EYA inhibitors could be used as neo-adjuvant therapy to improve the sensitivity of DNA damaging cancer treatments such as radiation and some forms of chemotherapy." (PMID 24367676, 2013).
tumor (9 papers, 2015 to 2025). "We found that higher mRNA expression of EYA3 was significantly associated with longer OS and PFI of ccRCC, suggesting that EYA3 could function as a tumor suppressor." (PMID 37156847, 2023). "This suggests that miR-708 functions as a tumor suppressor, counteracting the effects of EYA3-mediated chemoresistance." (PMID 40429954, 2025). "EWS-FLI1 represses miR-708 expression, leading to an increase in EYA3, which in turn increases tumor cell survival and resistance to chemotherapeutic agents." (PMID 40429954, 2025). "It has been reported that restoring miR-708 expression in ES cells reduces EYA3 levels, impairs DNA repair mechanisms, and sensitizes tumor cells to DNA-damaging agents such as etoposide and doxorubicin." (PMID 40429954, 2025). "EWSR1::FLI1 repressed miR-708 expression to indirectly induce EYA3 transcription, and inhibited expression of the tumor suppressive miR-145, and other miRNAs including miR-22, miR29a, miR-100, miR-125b, miR-221/222 and miR-271 to modulate tumor growth." (PMID 36672331, 2023). "The C-terminal of EYA3 is highly conserved, while the N-terminal is poorly conserved, which is closely related to tumor progression and treatment tolerance." (PMID 34395419, 2021). "IHC was further performed and indicated that circGNG4 knockdown inhibited the ki67 and EYA3 expression in the tumor tissues." (PMID 34395419, 2021). "Notably, the lowest mRNA expression of EYA1/2 was observed in tumor grade 2, whereas the lowest mRNA expression of EYA3/4 was found in grade 4." (PMID 37156847, 2023). "As the tumor grade increased, the mRNA expression level of EYA3/4 decreased." (PMID 37156847, 2023). "The results showed that overexpression of EYA1 could contribute to ccRCC development, while low expression of EYA3/4 might have a tumor-suppressive effect." (PMID 37156847, 2023). "EYA3 is closely associated with tumor progression and low levels of treatment success, and interacts with cellular inhibitor of PP2A (PP2A) to increase the stability of c-Myc, thus promoting tumor development." (PMID 34395419, 2021). "Understanding the molecular mechanism of how c-Myc is regulated (such as by Eya3 and PP2A) provides an alternative approach through which c-Myc may be targeted in the many tumor types in which it is implicated." (PMID 29535359, 2018). "The increased expression of EYA1 might play an important role in ccRCC oncogenesis, and the decreased expression of EYA3/4 could function as a tumor suppressor, suggesting EYA1/3/4 might serve as valuable prognostic markers and potential new therapeutic targets for ccRCC." (PMID 37156847, 2023). "Furthermore, as the tumor grade increased, a decrease in mRNA expression of EYA3/4 was observed." (PMID 37156847, 2023). "Thus, although PP2A is considered to be tumor suppressive, it may stimulate tumor progression when certain regulatory subunits bind to a protein, such as Eya3." (PMID 29535359, 2018). "miR-708 has been identified as a key regulator of tumor progression and chemoresistance in ES, acting through the modulation of EYA3 (Eyes Absent Homolog 3), a tyrosine phosphatase involved in DNA damage repair." (PMID 40429954, 2025). "Moreover, the EYA3 inhibitor benzarone blocks the transcription complex formation, MMPs, VEGFD, and EGFR expression, as well as tumor growth, and neoplastic cell invasion capacity in mouse tumor xenograft and in vitro cell models." (PMID 38069210, 2023). "Because the H79A mutation disrupts the Eya3 interaction with the B55α subunit of PP2A, the difference between Eya3H79A and Eya3WT suggests that B55α could act to promote tumor progression, rather than suppress it, a property normally attributed to PP2A24,46." (PMID 29535359, 2018).
tumor (continued). "We further demonstrate that Eya3 regulates the stability of c-Myc not via an intrinsic Thr phosphatase activity, but rather by controlling the dephosphorylation of c-Myc at pT58 through PP2A, suggesting that Eya3 may change the function of PP2A from tumor suppressive to tumor promotional." (PMID 29535359, 2018).
EYA3 also shares sentences with these, for which no sentence is quoted: asthma (1 paper).